AGR2 (anterior gradient 2, protein disulphide isomerase family member)
Diseases named in the same sentence as AGR2 in open-access papers (continued):
Sharing a sentence is not in itself a finding about the gene and the disease.
breast cancer (continued). "In a breast cancer model, the AGR2 levels were found to become increased in response to hypoxia, which was due to Twist1 binding to an E-box sequence within the AGR2 promoter and triggering of AGR2 gene transcription." (PMID 32268506, 2020). "AGR2 was also found in other types of cancer that are related to hormone-dependence such as breast cancer, prostate cancer and ovarian cancer." (PMID 33005802, 2020). "Next, we examined if AGR2 had an impact on doxorubicin-sensitivity in breast cancer cells, through modulating expression of AGR2 with AGR2-shRNA or AGR2-over-expression vectors." (PMID 30665445, 2019). "In breast cancer cells, an antibody (18A4 mAb) that showed a specific binding to AGR2 in the cytoplasm using immunofluorescent staining was revealed to inhibit the growth of the breast cancer cell line MCF7." (PMID 31247903, 2019). "AGR2 was shown to be a target of ER, which regulates expression of AGR2 in both normal mammary gland and breast cancer." (PMID 30665445, 2019). "Up-regulation of miR-135b-5p suppressed expression of AGR2 increasing doxorubicin-sensitivity of breast cancer cells." (PMID 30665445, 2019). "ER binds directly to AGR2 promoter to activate transcription of AGR2 in both cell lines and tumor samples of breast cancers." (PMID 30665445, 2019). "Consistent with our in vitro findings, a positive correlation between LINC02273 and AGR2 was confirmed in both primary tumors and metastatic LNs from breast cancer patients." (PMID 31856843, 2019). "Li and colleague had shown that AGR2 stabilized hypoxia inducible factor-1α enhancing hypoxia-induced doxorubicin resistance in breast cancer cells." (PMID 30665445, 2019). "Growing evidence has been demonstrated that AGR2 is overexpressed in prostate cancer, lung cancer, breast cancer, and pancreatic cancer, and promotes cell proliferation, invasion, and metastasis via multiple mechanisms." (PMID 30647455, 2019). "miR-135b-5p negatively regulates expression of AGR2 which increased sensitivity to doxorubicin in breast cancer cells both in vitro and in vivo." (PMID 30665445, 2019). "miR-135b-5p negatively regulated expression of AGR2 through targeting 3′-UTR confirmed that AGR2 is a target gene of miR-135b-5p in breast cancer cells." (PMID 30665445, 2019). "To assess the correlation between expression of AGR2 and doxorubicin-sensitivity in breast cancer cells, we analyzed expression of AGR2 mRNA in MDA-MB-231 and MCF-7 cells as well as doxorubicin-resistant MCF-7/DOXR cells." (PMID 30665445, 2019). "Our data on clinical breast cancer samples also showed that ER-positive tumors expressed higher levels of AGR2 than ER-negative ones." (PMID 30665445, 2019). "Over-expression of AGR2 alone seems insufficient for tumorigenesis of breast cancer, but rather can contribute to drug resistance." (PMID 30665445, 2019). "Previous studies have demonstrated the oncogenic role of AGR2 in several solid tumors including breast cancer." (PMID 31856843, 2019). "Expression level of AGR2 correlated with doxorubicin-sensitivity of breast cancer cells in our study." (PMID 30665445, 2019). "Our finding is indicative for an important role of miR-135b-5p/AGR2 pathway in regulating doxorubicin-sensitivity of breast cancer cells." (PMID 30665445, 2019). "In the breast cancer cell line T47D, silenced AGR2 protein was shown to downregulate cyclin D1, c-Myc and survivin, which play a critical role in cell growth." (PMID 31247903, 2019). "As expected, the mobility and invasiveness breast cancer cells were substantially increased in AGR2-overexpressed MDA-MB-231 and BT549 cells." (PMID 31856843, 2019).
breast cancer (continued). "AGR2 was also observed in the breast cancer cell lines MCF7 and H1299 to specifically bind to another protein called RuvB-like 2 (RUVBL2), which is involved in DNA repair, transcription regulation and chromatin structural control." (PMID 31247903, 2019). "AGR2 has been reported to play a critical role in oestrogen receptor (ER) positive breast cancer development." (PMID 31732481, 2019). "In prostate, AGR2 is overexpressed in cancer cells compared with normal luminal cells, and a majority of primary prostate tumors are AGR2 positive, This pattern is similarly found in pancreatic, oral, and breast cancers." (PMID 31303962, 2019). "Multivariant COX regression analysis also indicated that high LINC02273/high AGR2 expression is an independent prognostic factor in breast cancer (HR = 2.528, P = 0.001)." (PMID 31856843, 2019). "The pro-oncogenic anterior gradient 2 (AGR2) is involved in tumor growth and drug resistance of breast cancer." (PMID 30665445, 2019). "Since levels of miR-342-3p and miR-217 positively correlated with level of AGR2 in breast cancer cells, we deduce that miR-135b-5p is a more dominant regulator of AGR2-expression in breast cancer, comparing with miR-342-3p and miR-217." (PMID 30665445, 2019). "Doxorubicin treatment induced down-regulation of miR-135b-5p is a probable reason for over-expression of AGR2 in breast cancer, which is indicative for a treatment related drug resistance." (PMID 30665445, 2019). "Clinical breast cancer samples were collected and subjected to analysis for expression of AGR2 protein and miR-135b-5p." (PMID 30665445, 2019). "Among these candidate miRNAs, down-regulation of miR-135b-5p was in parallel with up-regulation of AGR2 in breast cancer cells." (PMID 30665445, 2019). "miR-135b-5p negatively regulated AGR2-expression of breast cancer cells increasing doxorubicin-sensitivity." (PMID 30665445, 2019). "In stages I and II tumors of different breast cancer types, 232 out of 351 breast cancers (66%) treated with adjuvant hormonal therapy showed positive staining of AGR2." (PMID 31247903, 2019). "In this study, expression levels of AGR2 and miR-135b-5p were analyzed in different breast cancer cell lines as well as in clinical breast cancer tissues." (PMID 30665445, 2019). "A study showed that the AGR2 protein expression level in the samples from breast cancer patients, who were previously treated with tamoxifen, was higher than that in those who had not been treated with tamoxifen." (PMID 31247903, 2019). "Decreased levels of miR-135b-5p correlated with over-expression of AGR2 in breast cancer cells during doxorubicin treatment." (PMID 30665445, 2019). "Over-expression of AGR2 is involved in pathogenesis of breast cancer including growth, drug resistance and metastasis of tumors, which is associated with poor prognosis." (PMID 30665445, 2019). "Based on the important roles of AGR2 and miRNAs in breast cancer, we interrogated how miRNAs regulate expression of AGR2 in breast cancer cells." (PMID 30665445, 2019). "The AGR2 gene was identified later in a gene expression profiling study in the MDA-MB-231 breast cancer cell line to promote survival and invasion under stressed and hypoxic conditions." (PMID 31247903, 2019). "Intrinsic or acquired over-expression of AGR2 was shown to mediate resistance to hormone therapies in estrogen receptor (ER)-positive breast cancers." (PMID 30665445, 2019). "Our results highlight the potential of miR-135b-5p as a target for treating AGR2-expressing breast cancer with doxorubicin-resistance." (PMID 30665445, 2019). "The examination of the AGR2 protein levels in 61 breast carcinomas patients by IHC revealed their overexpression, which was associated with lower tamoxifen treatment efficacy." (PMID 31247903, 2019). "Anterior Gradient 2 (AGR2) is a protein disulfide isomerase in the endoplasmic reticulum first discovered in ER+ breast cancer cells." (PMID 29796176, 2018).
breast cancer (continued). "Here, primary tumor mRNA data from women in the Molecular Taxonomy of Breast Cancer International Consortium (METABRIC) breast cancer cohort were analyzed for AGR2 expression and disease-specific survival." (PMID 29796176, 2018). "It is possible that breast cancer cells that fail to upregulate AGR2 likewise fail to mount a successful pro-survival UPR that restores endoplasmic reticulum homeostasis, thus succumbing to pro-death UPR signals that promote apoptosis and inflammation." (PMID 29796176, 2018). "Intracellular versus secreted AGR2 had different roles in enhancing breast cancer fulvestrant resistance." (PMID 29796176, 2018). "In breast cancer, there is a statistically significant correlation between AGR2 expression and response to tamoxifen." (PMID 29937991, 2018). "Breast cancer cell lines transfected with AGR2 produced metastasis in a xenograft model, showed gain of anchorage-independent growth and promoted tumor growth." (PMID 30140383, 2018). "As a result, we also evaluated the anti-migratory potential of H10 in the metastatic breast cancer cell line (MDA-MB-231) with modest expression of AGR2." (PMID 29937991, 2018). "Estradiol treatment of ER+ breast cancer cell lines stimulates both AGR2 expression and a twofold increase in ESR1 binding to the AGR2 promoter region as detected by chromatin immunoprecipitation (ChIP)." (PMID 29796176, 2018). "AGR2 knockdown by siRNA, shRNA, and miRNA in ER+ breast cancer lines reduces growth, survival, and migration, as well as fulvestrant and tamoxifen resistance." (PMID 29796176, 2018). "Intriguingly, it seems paradoxical to the prognosis of breast cancer patients for whom AGR2’ s high expression predicted poor outcomes." (PMID 29138453, 2017). "Excluding breast cancer, AGR2 overexpression was also found to have a significant correlation with poor OS in the remaining solid tumour patients (HR 1.51, 95% CI 1.04–2.19)." (PMID 29138453, 2017). "To fully elucidate AGR2′s clinical relevance in breast cancer, we assessed the relationship between AGR2 overexpression and clinicopathological features of breast cancer patients." (PMID 29138453, 2017). "The subgroup analysis on ER status also confirmed the unfavourable impact of AGR2 overexpression on the OS of ER positive breast cancer patients (HR 2.58, 95% CI 1.06–6.26)." (PMID 29138453, 2017). "In subgroup analysis for breast cancer, both HR estimates for OS and TTP (OS: HR 3.02, 95% CI 1.03–8.81; TTP: HR 1.93, 95% CI 1.17–3.20) further indicates that AGR2 overexpression is predictive of poor prognosis in breast cancer patients." (PMID 29138453, 2017). "To develop a suitable biomarker panel for early breast cancer detection, we measured AGR2 protein in human serum samples in parallel." (PMID 25875093, 2015). "AGR2 overexpression in primary breast cancer is correlated with poor response to tamoxifen treatment, which is Akt dependent." (PMID 25871396, 2015). "AGR2 was identified as being differentially expressed in estrogen receptor (ERα) positive breast cancer cell lines." (PMID 26445321, 2015). "We propose that the identification of the mechanism linking the IGF-1/insulin signal and AGR2 promoter activation is important, because it provides insights into the development of anti-breast cancer drugs." (PMID 25956506, 2015). "Our findings suggest AGR2 induction as a novel IGF-1-induced breast cancer formation mechanism, relevant to both the activation of the ER and the non-ER pathways." (PMID 25956506, 2015). "To further confirm how AGR2 induction contributes to IGF-1-induced breast cancer development, we investigated AGR2-knockdown effect on the IGF-1-induced cell proliferation, cell migration and cell cycle distribution." (PMID 25956506, 2015).
breast cancer (continued). "Using a well-established commercial ELISA for AGR2, we detected significantly elevated AGR2 protein levels in breast cancer sera in comparison to healthy controls." (PMID 25875093, 2015). "Increased AGR2 expression contributes to metastasis because of its capacity to enhance migration of breast cancer and oral squamous cell carcinoma in vitro and in vivo." (PMID 25871396, 2015). "AGR2 has been reported to be overexpressed in several human cancers, including estrogen receptor (ER)-positive breast cancer." (PMID 25956506, 2015). "Recent reports showed that aberrant AGR2 expression helps breast cancer cells survive under serum-depleted conditions and/or hypoxic culture conditions, promotes angiogenesis, and increases cell invasion." (PMID 25871396, 2015). "AGR2, as a novel biomarker for breast cancer, has already become a recent research topic of interest." (PMID 25956506, 2015). "Strikingly, AGR2 expression is increased over sevenfold in the presence of estrogen in hormone-dependent breast cancer cells." (PMID 25956506, 2015). "AGR2 can regulate breast cancer cells growth and survival by modulating Survivin, C-myc, and Cyclin D1." (PMID 25871396, 2015). "We revealed a highly significant elevation (P < 0.001, median FC: 2.2) of AGR2 protein level in breast cancer sera compared to controls." (PMID 25875093, 2015). "AGR2 promotes metastasis of breast cancer, hepatocellular carcinoma and head and neck squamous carcinoma cells." (PMID 25367337, 2014). "Human and murine AGR2 (Gob-4) expression was first identified in estrogen receptor (ER)-positive breast cancer cells and in goblet cells of the stomach, small intestine and colon, respectively." (PMID 25367337, 2014). "AGR2 is frequently overexpressed in many human cancers, including breast carcinoma, lung adenocarcinoma, ovarian carcinoma, and prostate cancers." (PMID 24717913, 2014). "AGR2 has also been investigated as a potential biomarker for hormone-responsive breast cancer in estrogen receptor-α-positive breast cancer cell lines." (PMID 23245351, 2012). "In human breast cancer cells, AGR2 expression correlates positively with estrogen receptor and negatively with epidermal growth factor receptor expression." (PMID 20525245, 2010). "These pathways were conversely modulated on treatment of a breast cancer line with recombinant AGR2." (PMID 20525379, 2010). "Studies have found that AGR2 expression can be increased in response to physiological stress in breast cancer cells and can enhance survival of damaged lung cancer cells." (PMID 21144054, 2010). "Altogether, our results demonstrate a critical role for AGR2 in breast cancer growth and survival, identify downstream signaling of AGR2, and thus support AGR2 as a promising oncology target for therapeutic agents." (PMID 20525379, 2010). "Anterior gradient-2 (AGR2) is a secreted protein that was originally identified to be coexpressed with ER in breast cancer cell lines." (PMID 20525379, 2010). "Breast cancer drivers (ER and cyclin D1) as well as cancer-signaling nodes (pSrc, c-Myc, and survivin) were demonstrated to be downstream of AGR2." (PMID 20525379, 2010). "AGR2 is the human homolog of the protein XAG-2 in Xenopus laevis and was first identified as differentially expressed in estrogen receptor positive breast cancer cell lines." (PMID 21144054, 2010). "Removal of AGR2 has an impact on cancer-relevant pathways, including the cell cycle and E2 signaling, ultimately resulting in cell death, thus demonstrating that AGR2 plays a critical role in breast cancer progression." (PMID 20525379, 2010). "AGR2 is commonly overexpressed in cancers, and our data suggest an important functional role for AGR2 in breast cancer." (PMID 20525379, 2010). "Its upregulation has been well documented in a number of cancers, particularly breast cancer, for which mixed data exist on the prognostic implications of AGR2 expression." (PMID 20525379, 2010).
breast cancer (continued). "AGR2 affects key breast cancer drivers, including cyclin D1, c-Myc, and ER, as well as more general oncogenic signaling nodes such as p-Src and survivin." (PMID 20525379, 2010). "The role of endogenous AGR2 in breast cancer cell proliferation was assessed with anchorage-dependent and anchorage-independent growth assays." (PMID 20525379, 2010). "Overall, 64.8% of breast cancers stained for AGR2 using a 1% cutoff to differentiate the negatively and positively staining tumours." (PMID 16598187, 2006). "The anterior gradient protein-2 (AGR2) is inducible by oestrogen and itself can induce metastasis in a rat model for breast cancer." (PMID 16598187, 2006). "Here, a rabbit antibody to recombinant human AGR2 was used to assess its prognostic significance in a retrospective cohort of 351 breast cancer patients treated by adjuvant hormonal therapy." (PMID 16598187, 2006). "The aim of this study is to examine for the first time the expression of AGR2 in specimens of primary breast carcinomas so as to assess its relationship with other tumour variables and with patients' survival in a group of patients treated by hormonal therapy." (PMID 16598187, 2006). "Antiserum to human AGR2 detected a band of 18 kDa in Western blots of extracts from primary breast carcinomas that were positive in immunocytochemical staining for AGR2." (PMID 16598187, 2006). "Staining of primary breast carcinomas for AGR2 showed great variation from tumour to tumour in the proportion of cancer cells staining, ranging from none to >90%." (PMID 16598187, 2006). "In addition, blocking the downstream pathways activated by LYPD3 and its ligand AGR2 facilitated the progress of endocrine therapy-resistant breast cancer and pancreatic carcinoma 76,77." (PMID 40084259, 2025). "The insight into the intricate interplay between AGR2-involved ER stress, autophagy, and unconventional secretion provides a foundation for refining strategies aimed at impeding metastasis in both canine mammary tumors and potentially human cancers." (PMID 38822246, 2024). "Moreover, insights into the mechanisms of resistance to tamoxifen and doxorubicin in breast cancer have suggested the presence of AGR2 in the ECM." (PMID 39062458, 2024). "At the same time, the interaction with C4.4a and DAG-1 proteins may be a feasible target for the intervention of estrogen responsive breast cancer, which promotes researchers’ interest in the research of proteins interacting with AGR2." (PMID 37197416, 2023). "A methyltransferase METTL3 may modify MALAT1 protein through N6 methyladenosine (m6A), recruit E2F1 and activate the expression of downstream AGR2, thus promoting the adriamycin resistance in breast cancer." (PMID 37197416, 2023). "Considering that the mutation of ATP binding site of Reptin will affect its oligomerization level, thermal stability and stability of binding with AGR2, the modification of ATP binding site is of great significance to explore the role of Reptin-AGR2 complex in the growth of breast cancer cells." (PMID 37197416, 2023). "This review also enumerates the role of AGR2 in the progress and prognosis of breast cancer, and emphasizes that AGR2 can be a promising biomarker and a target for immunotherapy of breast cancer, providing new ideas for early diagnosis and treatment of breast cancer." (PMID 37197416, 2023). "In breast cancer, AGR2 co exists with estrogen receptor and is induced by estrogen." (PMID 37197416, 2023). "At the same time, the combination of AGR2 and other biomarkers may be a promising strategy to improve the accuracy of early breast cancer detection." (PMID 37197416, 2023). "They showed that inhibiting the activity of this pathway with blocking antibodies against LYPD3 or AGR2 inhibited the growth of endocrine therapy resistant breast cancer in the preclinical model, and again provided the basis for the development of humanized antibodies against AGR2." (PMID 37197416, 2023).